RPS23 (ribosomal protein S23)
Description:
Component of the ribosome, a large ribonucleoprotein complex responsible for the synthesis of proteins in the cell. The small ribosomal subunit (SSU) binds messenger RNAs (mRNAs) and translates the encoded message by selecting cognate aminoacyl-transfer RNA (tRNA) molecules. The large subunit (LSU) contains the ribosomal catalytic site termed the peptidyl transferase center (PTC), which catalyzes the formation of peptide bonds, thereby polymerizing the amino acids delivered by tRNAs into a polypeptide chain. The nascent polypeptides leave the ribosome through a tunnel in the LSU and interact with protein factors that function in enzymatic processing, targeting, and the membrane insertion of nascent chains at the exit of the ribosomal tunnel. Plays an important role in translational accuracy. Part of the small subunit (SSU) processome, first precursor of the small eukaryotic ribosomal subunit. During the assembly of the SSU processome in the nucleolus, many ribosome biogenesis factors, an RNA chaperone and ribosomal proteins associate with the nascent pre-rRNA and work in concert to generate RNA folding, modifications, rearrangements and cleavage as well as targeted degradation of pre-ribosomal RNA by the RNA exosome.
Synonyms: S23; uS12; BTDD; MABAS; MCINS; PAMAS
Tractability: Small molecule: an approved drug acts on it; a structure with a bound ligand is known; a high-quality ligand is known. PROTAC: UniProt records ubiquitination sites on it; ubiquitination databases record sites on it; its protein half-life has been measured; a small molecule that binds it is known. Other modalities: a drug acting on it is in phase 2 or 3 trials.
Target class: Other cytosolic protein
Gene: Protein-coding gene on chromosome 5 (82,273,320 to 82,278,414, reverse strand). Ensembl gene ENSG00000186468.
Subcellular location: Cytoplasm, cytosol; Cytoplasm; Rough endoplasmic reticulum; Nucleus, nucleolus
Subcellular location (Human Protein Atlas): Cytosol; Endoplasmic reticulum
Pathways (Reactome):
Metabolism of proteins: Eukaryotic Translation Termination; Formation of a pool of free 40S subunits; Formation of the ternary complex, and subsequently, the 43S complex; GTP hydrolysis and joining of the 60S ribosomal subunit; L13a-mediated translational silencing of Ceruloplasmin expression; PELO:HBS1L and ABCE1 dissociate a ribosome on a non-stop mRNA; Peptide chain elongation; Protein hydroxylation; Ribosomal scanning and start codon recognition; SRP-dependent cotranslational protein targeting to membrane; Translation initiation complex formation; ZNF598 and the Ribosome-associated Quality Trigger (RQT) complex dissociate a ribosome stalled on a no-go mRNA
Disease: SARS-CoV-1 modulates host translation machinery; SARS-CoV-2 modulates host translation machinery; Viral mRNA Translation
Metabolism of RNA: Major pathway of rRNA processing in the nucleolus and cytosol; Nonsense Mediated Decay (NMD) enhanced by the Exon Junction Complex (EJC); Nonsense Mediated Decay (NMD) independent of the Exon Junction Complex (EJC)
Cellular responses to stimuli: Response of EIF2AK4 (GCN2) to amino acid deficiency
Developmental Biology: Regulation of expression of SLITs and ROBOs
Metabolism: Selenocysteine synthesis
Gene Ontology:
Molecular function: protein binding; RNA binding; structural constituent of ribosome
Biological process: cytoplasmic translation; maintenance of translational fidelity; ribosomal small subunit biogenesis; stress granule assembly; translation
Cellular component: cytosol; cytosolic ribosome; cytosolic small ribosomal subunit; membrane; small-subunit processome; cytoplasm; nucleoplasm; ribosome; rough endoplasmic reticulum; nucleolus; small ribosomal subunit; synapse
Genetic constraint (gnomAD): Loss-of-function variants: 0 observed, 16.27 expected, observed/expected ratio (o/e) 0, 90% interval 0 to 0.18. The upper end of that interval is the gene's LOEUF score, 0.18, which puts it in group 1 of 6, group 1 being the genes least tolerant of losing a copy. Missense variants: 73 observed, 182.08 expected, observed/expected ratio (o/e) 0.4, 90% interval 0.33 to 0.49. Synonymous variants: 66 observed, 62.82 expected, observed/expected ratio (o/e) 1.05, 90% interval 0.86 to 1.29.
Homologues: Orthologues: chimpanzee RPS23 (100% identical), macaque RPS23 (100% identical), mouse Rps23 (100% identical), pig RPS23 (100% identical), rat Rps23 (100% identical), zebrafish rps23 (99% identical), tropical clawed frog rps23 (97% identical), Drosophila melanogaster RpS23 (91% identical), Caenorhabditis elegans rps-23 (85% identical). Paralogues in human: MRPS12 (29% identical).
Diseases named in the same sentence as RPS23 in open-access papers:
RPS23 is named in the same sentence as 38 diseases in open-access papers, as found by Europe PMC text mining. Sharing a sentence is not in itself a finding about the gene and the disease. The quoted sentences say what the papers report.
microcephaly (5 papers, 2020 to 2025). A congenital or acquired developmental disorder in which the circumference of the head is smaller than normal for the person's age and sex. "Brain defects have been found in patients carrying a mutated Rpl10 or Rps23, as they show an increased incidence in microcephaly, seizures, aphasia, ataxia, and intellectual disability." (PMID 35281111, 2022). "We prioritized these four RP genes due to their involvement in human ribosomopathies, with rpl-5, rpl-33, and rps-10 relating to DBA, and rps-23 relating to microcephaly and intellectual disability without the blood phenotypes." (PMID 39786340, 2025).
breast carcinoma (4 papers, 2013 to 2024). "Five of these were strong cross-tissue eQTLs in GTEx (for ATG10, ATP6AP1L, and RPS23, all associated with rs7707921, and C5orf35 (also known as SETD9) and rs889312; P < 1 × 10− 5 in at least 19 tissues with concordant directionality) and maintain their regulatory capacity in breast cancer cells." (PMID 30205839, 2018). "It is worth noting that in this study, 8 (ACTR3, ARF4, PGRMC1, RPS23, WDR12, ACTR2, SIAH1, and RPS27L) of 12 hub genes are related to cancers, such as lung cancer, epithelial ovarian cancer, gastric cancer, glioblastoma, breast cancer, and esophageal cancer." (PMID 33391181, 2020).
autism spectrum disorder (2 papers, 2022 to 2024). A spectrum of developmental disorders that includes autism, and Asperger syndrome. "In particular, mutations in rpS23 and rpL10 have been shown to be associated with autism spectrum disorder, a disorder that has been associated with aberrant 5-HT function." (PMID 36048889, 2022).
disc degeneration (2 papers, 2020 to 2023). "The genes encode ribosomal proteins, such as RPS23, among others, which are enriched in biological processes of translation, translation elongation, and RNA processing in disc degeneration." (PMID 36980356, 2023). "RPS23 is involved in the protein synthesis processes and progression of disc degeneration (DD), suggesting its potential use in the diagnosis and therapy of DD." (PMID 33391181, 2020).
colorectal cancer (1 paper, 2024). A primary or metastatic malignant neoplasm that affects the colon or rectum. "In the context of gastric cancer, RPL15, RPL6 and RPS13 exhibited upregulated expressions, while in colorectal cancer, RPS18, RPS23, RPL28 and RPL32 were found to be downregulated, implicating these ribosomal proteins as potential diagnostic markers for gastric and colorectal cancers, respectively." (PMID 39684863, 2024).
coronary heart disease (1 paper, 2024). "Another study confirmed that miR-338-3p/RPS23 was involved in the progression of coronary heart disease." (PMID 38613636, 2024).
gastric cancer (1 paper, 2020). A primary or metastatic malignant neoplasm involving the stomach. "Another study showed that RPS23 is a hub gene in gastric cancer." (PMID 33391181, 2020).
leukemia (1 paper, 2025). A malignant (clonal) hematologic disorder, involving hematopoietic stem cells and characterized by the presence of primitive or atypical myeloid or lymphoid cells in the bone marrow and the blood. "We used K562 leukemia cell line to examine the impacts of reduced levels of specific RP transcripts, RPS10, RPL35A (the ortholog of C. elegans rpl-33), RPL5, and RPS23." (PMID 39786340, 2025).
meningioma (1 paper, 2020). A generally slow growing tumor attached to the dura mater. "Grade-wise comparisons on MGI (benign) vs MGII (atypical) meningiomas revealed prominent involvement of TIMM50, SEC23A, MTAP, RPS23, and ADRM1 based on the concordance analysis of highly ranked features from across 20 Machine Learning randomized iterations obtained via the methods of the Ball group." (PMID 32974197, 2020).
pulmonary hypertension (1 paper, 2022). Increased pressure within the pulmonary circulation due to lung or heart disorder. "To further investigate the relationships among the SRP-DGs and risk of SSc-PH, we constructed a nomogram model using seven SRP-DGs (RPL32, RPS12, RPS14, RPS23, RPS3, RPS7, and SRP9) to predict the risk of pulmonary hypertension complications in patients with SSc." (PMID 36518216, 2022).
cancer (5 papers, 2013 to 2025). A tumor composed of atypical neoplastic, often pleomorphic cells that invade other tissues. "The increased expression of hub genes GNL2, RPS23, and IMP4 was not significant in GEPIA, but other studies have reported the increased expression of GNL2, RPS23, and IMP4 in cancer." (PMID 39949372, 2025).
infection (4 papers, 2017 to 2022). The state of being infected such as from the introduction of a foreign agent such as serum, vaccine, antigenic substance or organism. "ASFV-infected cells showed significantly increased RPS23 relative expression levels at early time points (1, 2, 4 hpi) followed by a drop to mock-infected cells levels at later post-infection times (6–24 hpi)." (PMID 33384682, 2020).
RPS23 also shares sentences with these, for which no sentence is quoted: tumor (7 papers); glioblastoma (3); epithelial ovarian cancer (2); Intellectual disability (2); viral infection (2); Aphasia (1); Ataxia (1); B-cell lymphoma (1); basal cell carcinoma (1); Brachycephaly (1); cancer of female genital organs (1); cancer of male genital organs (1); coenzyme Q10 deficiency (1); colon adenocarcinoma (1); developmental delay (1); epilepsy (1); esophageal cancer (1); lung carcinoma (1); melanoma (1); neuroblastoma (1); osteosarcoma (1); ovarian cancer (1); Seizure (1); Sepsis (1); skin cancer (1); trichomegaly (1).